MTOR (mechanistic target of rapamycin kinase)
Diseases named in the same sentence as MTOR in open-access papers (continued):
Sharing a sentence is not in itself a finding about the gene and the disease.
cancer (continued). "We tested the effect of JHU-083 on cell proliferation, metabolism, and mTOR signaling in cancer cell lines." (PMID 33681764, 2021). "A hybrid of phenylsulfonylfuroxan and coumarin induced caspase-dependent cell death, autophagy, and suppressed PI3K/Akt/mTOR signaling pathway to kill cancer cells." (PMID 33768214, 2021). "Aberrant activity of PI3K/Akt/mTOR has been detected in multiple forms of human cancer due to the abnormal activation of both Akt and S6 or the phosphatase and tensin homolog (PTEN) suppression in cancer cell lines." (PMID 34452154, 2021). "Based on this observation, rapamycin can inhibit the TGFβ-dependent PI3K/Akt/mTOR activation and influence the migratory and invasive features of cancer cells." (PMID 35029792, 2021). "Inhibition of mTOR-related autophagy has been shown to have potential for cancer treatment and prevention." (PMID 34093717, 2021). "Beside cancers, loss of FBXW7 also contributes to other mTOR-related diseases, such as metabolic disorders and aging, which warrants further studies." (PMID 33670113, 2021). "The PI3K/AKT/mTOR signaling pathway is an important signaling pathway in cancer, which is active in most cancers and plays an important role in cancer biology." (PMID 34853601, 2021). "Aberrant hyperactivation of the mTOR pathway in cancer mainly results from different levels of mechanisms and its signal cascade." (PMID 35250965, 2021). "GO and KEGG enrichment analysis showed that the target genes were mainly enriched in the MAPK signaling pathway, PI3K-AKT signaling pathway, proteoglycans in cancer signaling pathway, and the mTOR signaling pathway." (PMID 33816220, 2021). "In summary, the IGF-1 R-PI3K-Akt-mTOR signaling pathway is over-activated in numerous cancers and is involved in the local anesthetic agent-mediated anti-proliferative and pro-apoptotic progression." (PMID 34696683, 2021). "Canonically, blockade of FGFR signalling led to the attenuation of the Ras/Raf/Mek/Erk and PI3K/Akt/mTOR pathways, leading to a decrease in the expression of proteins involved in cancer stemness." (PMID 33179425, 2021). "Another valuable target in tumor therapy is the mTOR pathway, described as being hyperactivated in 80% of human cancers, and particularly in cats mTOR is involved in metastization, invasion and tumor progression." (PMID 33800900, 2021). "Activation of the PI3K/AKT/mTOR pathway has been shown to promote growth, proliferation, and survival in cancer." (PMID 34164393, 2021). "Resveratrol has an ability to enhance autophagy and kill cancer cells by suppressing the phosphoinositide 3-kinase (PI3K)/A serine/threonine protein kinase (Akt)/mTOR signaling pathway and enhancing AMPK and sirtuin (SIRT1) pathways." (PMID 33768214, 2021). "mTOR is activated in a variety of malignant tumors and is an important regulator of cell proliferation and protein translation." (PMID 35155187, 2021). "The pathological relevance of mTOR signal dysregulation has been explained in many human diseases, especially in various human cancers." (PMID 34194607, 2021). "The first was to investigate the activity of mTOR and mTOR-related complexes in high-risk HPV-positive (UM-SCC47 and CaSki) and HPV-negative (SCC-4 and SAS) cancer cell lines." (PMID 33482765, 2021). "Cancer promotion can be regulated by several pathways associated with inflammation, such as those involving NF-κB, STAT3, mTOR, and MAPKs, which are triggered by pro-inflammatory cytokines like IL-6, TNF-α, and IL-1β." (PMID 34950252, 2021). "It is suggested that cell death machinery has been associated with modulation of PI3K/Akt/mTOR pathway as ISL suppressed the phosphorylation of Akt, PI3K, and mTOR in cancer cells." (PMID 34073042, 2021).
cancer (continued). "We then analyzed the differential expression of these 40 mTOR pathway genes in cancer and normal tissues and performed an HR analysis and coexpression analysis of these genes." (PMID 34194607, 2021). "In many cancers the activity of RARβ itself is suppressed via various pathways leading up to mTOR activation." (PMID 34178631, 2021). "Upregulation of the PI3K/AKT/mTOR pathway contributes to cancer cell survival, acquires chemoresistance, which was related to inhibition of apoptosis and cell cycle progression, differentiation and growth." (PMID 34975466, 2021). "Dysregulation and aberrant activation of mTOR is commonly detected in NSCLC, which is associated with tumorigenesis and cancer progression." (PMID 34178653, 2021). "Initial reports of reduced incidence of cancer among organ transplant recipients receiving treatment with mTOR inhibitors strongly suggest separate pathways for pharmacological immunosuppression and oncogenesis." (PMID 34093847, 2021). "Here, we report the efficacy of such personalized combination treatment regimens which achieve efficacious mTOR blockade as well as tandem targeting of other tumor vulnerabilities to yield meaningful outcomes in treatment of advanced refractory cancers." (PMID 33935721, 2021). "The effect of metformin on cancers has been suggested to be mediated either indirectly through insulin or directly through mammalian target of rapamycin (mTOR) modulation." (PMID 34436421, 2021). "On the other hand, BDNF increases tumor cell growth and metastasis via tyrosine kinase receptors via numerous pathways, such as Akt, MAPK, and the mammalian target of rapamycin (mTOR) in cancer." (PMID 34768930, 2021). "In prostate cancer, PI3K/Akt/mTOR/AR/MAPK/Wnt pathways cooperate to enhance cancer growth and drug resistance." (PMID 33668092, 2021). "The PI3K/Akt/mTOR pathway is a well-known signaling pathway involved in cancer development and progression." (PMID 34783291, 2021). "Taken together, NFATc2 mRNA expression appears to have a biologic connection with the mTOR pathway across cancer types." (PMID 34021224, 2021). "Based on the observations that rapamycin enhances the efficacy of vaccines targeting bacteria or virus, the effect of mTOR inhibitors on vaccines targeting cancer was investigated." (PMID 33802831, 2021). "The limited success of the allosteric inhibitor Rapamycin as an anti-cancer drug led to the development of ATP competitive mTOR inhibitors 30,31." (PMID 33390782, 2021). "mTOR is critical in the pathway and promotes cancer proliferation and metabolism upon overactivation, which is also an important target for cancer therapy." (PMID 34079798, 2021). "PI3k-Akt/mTOR signaling is frequently deregulated in human cancer that is one of the primary mechanisms for sustaining tumor outgrowth and metastasis." (PMID 34211002, 2021). "PI3K/AKT/mTOR signaling has also been reported as one of the most important intracellular pathways, and can be considered a master regulator for cancer." (PMID 34541602, 2021). "PI3K/AKT/mTOR pathway participates in a broad range of cancer regulatory processes, including cancer metabolism, proliferation and migration." (PMID 33613746, 2021). "Among mTOR proteins, mTORC1 is frequently activated in human cancers and targeting mTORC1 signaling is a promising strategy for tumor therapy." (PMID 34434284, 2021). "These preliminary evidences suggest the ability of CO-RMs to compromise the self-sufficiency of cancer cells in proliferative signals by inhibiting PI3K/Akt/mTOR pathway." (PMID 34507160, 2021). "SNHG15 is an lncRNA which plays critical roles in the development and progression of various cancers through regulation of Akt/mTOR signaling." (PMID 34439315, 2021). "In normal physiology, regulatory mechanisms tightly control the activity and homeostasis of the PI3K/AKT/mTOR pathway, but it can be constitutively activated in various cancers." (PMID 33572326, 2021).
cancer (continued). "Rapamycin analogs such as everolimus and ridaforolimus are the mTOR inhibitors that are widely used as anti-cancer agents." (PMID 37303943, 2021). "Previous results showed that HK2 was highly expressed in cancer tissues, and the expression of p-mTOR was decreased in BC cells when HK2 was silenced." (PMID 34345220, 2021). "PI3K/AKT/mTOR signaling pathway plays a crucial role in cancer development including proliferation, metastasis, survival, and angiogenesis." (PMID 34638601, 2021). "The present study provided evidence that PI3K/Akt/NF-κB/mTOR/STAT3/CDK6 signaling network collectively contributes to generating cancer stemness in GBM." (PMID 34572040, 2021). "To confirm the role of the AMPK/mTOR signaling in regulating LDHA‐induced cancer cell progression, we then pharmacologically inhibited AMPK expression with 20 μM Compound C, a selective and cell‐permeable AMPK inhibitor, in LDHA‐SH cells." (PMID 34185423, 2021). "This points that KRAS‐mediated regulation of AATs is crucial for the uptake of AAs, mTOR activation, and cancer cell proliferation." (PMID 34003553, 2021). "The orchestration of the cellular metabolism is not conducted by a single leader; the complex interplay between AMPK, mTOR, and other signaling network help to meet the conflicting self-requirement cancer cells." (PMID 34823530, 2021). "The phosphatidylinositol 3-kinase (PI3K)/v-akt murine thymoma viral oncogene homolog (Akt)/mammalian target of rapamycin (mTOR) signaling pathway plays a role in cell proliferation, cell cycle, apoptosis, and cancer cell metabolism." (PMID 33723724, 2021). "PI3K/AKT/mTOR signaling pathway overexpression has been reported in various cancers types, including CRC." (PMID 34638601, 2021). "PI3K/Akt/mTOR pathways are one of the main prosurvival pathways that are activated in human cancers." (PMID 34744708, 2021). "For instance, rapamycin is highly recommended to be used in cancer chemotherapy for its strong inhibition of mTOR pathway." (PMID 33958705, 2021). "Several studies reported that ULK1 inhibits cancer metastasis by promoting autophagy and interacting with the mTOR/AMPK pathway." (PMID 34671559, 2021). "Oncogenic KRAS signaling has been reported to affect glutamine transport, energy metabolism, and cancer cell proliferation through mTOR activation." (PMID 34003553, 2021). "Important intrinsic factors that adjust PD-L1 expression in cancer cells include the mechanistic target of rapamycin (mTOR), mitogen-activated protein kinase, and Myc." (PMID 34202980, 2021). "Due to its ability to inhibit mTOR pathway, studies in Deptor have been of great interest regarding cancer development and progression." (PMID 33412518, 2021). "The GPCR in turn then activates PI3K and downstream AKT and mTOR, leading to increased cell growth and proliferation in cancer cells." (PMID 34298770, 2021). "Lapatinib has been reported to inhibit the growth of cancer via the ERBB2/AKT/mTOR and RAF/MEK/ERK signaling pathways." (PMID 34459788, 2021). "mTOR hyperactivity can overwrite the metabolic checkpoints, contributing to cancer growth nutrient and growth factors independently." (PMID 35029792, 2021). "The PI3K/AKT signaling and their mammalian target of mTOR are key regulators of glycolytic reprogramming and cancer cell proliferation." (PMID 33931589, 2021). "EGFR is a major signal transducer of mitogens in cancer pathogenesis and the progression, upstream, of mTOR and is an important target in anticancer therapy." (PMID 33925400, 2021). "Cav1 was reported to block EGF-mediated proliferation, migration and invasion by targeting downstream effectors (mainly MEK/ERK and Pi3K/AKT/mTor) in various cancers." (PMID 34207120, 2021). "mTOR signaling is another key regulator of protein synthesis, which is frequently deregulated in cancers including NB." (PMID 34565342, 2021).
cancer (continued). "Much evidence has illustrated mTOR activation in numerous types of tumours, including PCa,8, 34 thus targeting mTOR has become a promising method for cancer therapy." (PMID 33507584, 2021). "Apitolisib (GDC-0980) is dual PI3K/mTOR inhibitor, which can induce apoptosis of cancer cells and inhibit cancer cell growth." (PMID 34768941, 2021). "The present study demonstrates that USP52 inhibits cancer cell proliferation through down-regulation of cyclin D1 (CCND1) as well as AKT/mTOR signaling pathway inhibition." (PMID 34533198, 2021). "In the present study, we found that inhibition of glycolysis suppressed LPS-induced mTOR phosphorylation, which was consistent with the findings from previous report which indicated that 2-DG was shown to inhibit mTOR in some cancer cell lines." (PMID 34107997, 2021). "Therapy targeting the PI3K/Akt/mTOR pathway has been suggested to overcome the drug resistance in TNBC by regulating apoptosis in BCSCs in addition to cancer cells." (PMID 34944829, 2021). "Mammalian target of rapamycin (mTOR) inhibitors and dopamine receptor antagonists can effectively reverse the glycolytic status of cancers." (PMID 34304708, 2021). "Despite the proven anticancer benefits of combined mTOR inhibitors and immunotherapy in preclinical models, several challenges exist when applying such treatment protocols in cancer patients." (PMID 33802831, 2021). "DEPTOR has been characterized as a modulator of mTOR activity with a profound impact on metabolism and cancer." (PMID 34519268, 2021). "During cancer initiation, autophagy regulators, such as mTOR and AMPK, are negatively modulated by tumor-suppressing factors, which cause autophagy induction." (PMID 34025409, 2021). "There are many PI3K/mTOR mixed inhibitors, but only a few have advanced in clinical cancer trials due to pharmacokinetic, tolerability, and safety issues." (PMID 33668092, 2021). "Ongoing trials will help identify the future role that kinase inhibitors of mTOR will endorse in cancer therapy." (PMID 33802831, 2021). "In sum, these studies have highlighted that mTOR pathway inhibitors are effective in cancer treatment, which has furthered research interest in their nature and application." (PMID 33925400, 2021). "The intricated network of PI3K signaling also acts as a central node for activating mTOR, NF-kB, GSK3ß, p27, and Bad-Bax pathways, which are known to regulate various aspects of cancer cell survival, growth, motility, and metabolism." (PMID 34503244, 2021). "The PI3K/AKT/mTOR signalling pathway plays an important role in numerous diseases, including cancer." (PMID 33949020, 2021). "The signaling network of PI3K, AKT, and mammalian target of rapamycin (mTOR) controls most hallmarks of cancer, including cell cycle, survival, metabolism, motility, and genomic instability." (PMID 34680615, 2021). "One of the most important metabolic roles of lipids is to partake in the autophagy process by participating in the mTOR complex which is an important target in the cancer cell survival signal." (PMID 34840582, 2021). "Through transferring of let-7a miRNA, hypoxic cancer exosomes suppress the insulin-Akt-mTOR signaling pathway and evade host immunity to enhance cancer progression." (PMID 34263260, 2021). "The PI3K/AKT/mTOR pathway is a major oncogenic driver that exerts vital functions in cancer growth, survival, and progression, and is frequently activated during carcinogenesis." (PMID 34162370, 2021). "PI3K/mTOR activation plays a significant role in maintaining cancer stem-like cells for in vitro colony formation ability, spheres formation capacity, and in vivo tumorigenicity." (PMID 33828530, 2021). "Integrated analysis showed that the differentially expressed mRNAs mainly regulated pathways in cancer, the cell cycle, pyrimidine metabolism, and the mTOR signaling pathway." (PMID 33681194, 2021). "mTOR pathway is one of the classical canonical pathways involved in cancer cell proliferation and metastasis." (PMID 33663585, 2021).
cancer (continued). "ROS is involved in apoptosis regulation by regulating Erk, JNKs, p38, and through the Akt/mTOR pathways in many types of cancers." (PMID 34503074, 2021). "mTOR negatively regulates autophagy that plays a key role in cancer progression and evolution in response to stressful stimuli." (PMID 34369083, 2021). "Concurrent pharmacologic targets of the RAF/MEK/ERK and PI3K/AKT/mTOR pathways have been reported in KRAS-driven cancer models, but clinically this strategy has been limited by additive toxicity." (PMID 35095481, 2021). "To further study the expression of mTOR pathway genes in different cancers, we used log2(FC) of the gene expression level between normal and cancer tissues." (PMID 34194607, 2021). "Several types of mTOR inhibitors such as rapamycin, its rapalogs, and dual mTORC1/mTORC2 inhibitors have been examined in various cancer models, including PDAC." (PMID 34638443, 2021). "Another compound, Asparagine, which has been transported from HA to HAS, was shown to have antiproliferative activity and to regulate mTOR signaling in cancer cells." (PMID 34444724, 2021). "Till date, several small molecule inhibitors of the PI3K/AKT/mTOR pathway have been investigated in preclinical studies; however, only a few inhibitors are currently approved for clinical treatment of human cancers." (PMID 34299129, 2021). "Several studies have reported the inappropriate PI3K/Akt/mTOR pathway regulation in different cancers, such as breast, liver, colorectal, prostate, and gastric cancer." (PMID 34830339, 2021). "On the other hand, stimulation of PI3K/AKT/mTOR signaling corresponded with fewer dormant cancer cells in tumor burden and improved response to cancer therapy." (PMID 34832087, 2021). "MTOR inhibitors were significantly enriched in all cancer types and have been reported to inhibit glycolysis-related tumorigenicity." (PMID 34304708, 2021). "Schedule-dependent PI3K/mTOR inhibition has a potential to reduce the frequency of side effects observed after PI3K/mTOR pathway inhibition by reducing number of administered doses required to achieve cytotoxic effects in cancer cells." (PMID 34065268, 2021). "Using integrative proteogenomic analysis, Zhang found that p-mTOR expression level was significantly correlated with improved outcomes in 32 major types of cancer including RCC, which was contradictory to the experimental results." (PMID 34458019, 2021). "Several studies suggest that the PI3K/AKT/mTOR pathway is often genetically altered in human cancers." (PMID 34298731, 2021). "The authors also observed that 4-chloro fascaplysin limited the growth of this carcinoma by activating the phosphoinositide 3-kinases, protein kinase B, and mechanistic target of rapamycin (PI3K/Akt/mTOR) pathway." (PMID 34203532, 2021). "The abnormal regulation of mTOR has been extensively reported within human carcinomas from several different origins and it is known that the PI3K–Akt pathway is the major upstream regulator of mTOR-signaling." (PMID 34452154, 2021). "The signal pathway of mTOR-HIF-1α-VEGF is activated in cancer cells; metformin or other AMPK activators can impede them, inhibiting angiogenesis." (PMID 32185076, 2020). "In the context of cancer, many projects have been conducted dedicated to developing inhibition strategies to effectively block the activation of mTOR signaling activity, with some promising clinical trials underway." (PMID 33371210, 2020). "In the BR and SR cancer cells, we observed several frequently activated pathways, such as the mTOR, Wnt, JAK/Stat, and PI3K/AKT signaling pathways, that have been shown to increase cell survival and proliferation." (PMID 32002127, 2020). "Erufosine inhibits the aberrant PI3K/Akt/mTOR signaling pathway in various cancer types including leukemia, oral squamous cell carcinoma, glioma and prostate cancer." (PMID 32410999, 2020).